AGR2 (anterior gradient 2, protein disulphide isomerase family member)
Diseases named in the same sentence as AGR2 in open-access papers (continued):
Sharing a sentence is not in itself a finding about the gene and the disease.
breast cancer (continued). "Extracellular AGR2 (eAGR2) is found to act synergistically with insulin-like growth factor-1 (IGF-1) to induce cell proliferation, migration, and epithelial–mesenchymal transition in breast cancer cells." (PMID 34679944, 2021). "A study revealed that the induction of the TGF-β SMAD regulatory pathway in the lung adenocarcinoma cell line A549, the breast cancer cell line BT-474, and the pancreatic adenocarcinoma cell line PANC-1, resulted in the significant downregulation of the levels of AGR2." (PMID 31247903, 2019). "Levels of AGR2 mRNA showed negative correlation with levels of miR-135b-5p and miR-194-5p in these breast cancer cells." (PMID 30665445, 2019). "Intriguingly, we also observed a negative correlation between levels of AGR2 and miR-135b-5p in clinical breast cancer samples." (PMID 30665445, 2019). "In a 20-year follow-up study, an immunocytochemical analysis of 315 stages I and II tumors of breast cancer patients separated samples into positive or negative AGR2 expressed tissues." (PMID 31247903, 2019). "For example, AGR2 has been identified by CES as an essential gene for the T47D cell line (breast cancer) but not others." (PMID 31732481, 2019). "A combined integration of the here identified putative serum biomarkers AGR2 and AGR3 into a microfluidic-based analysing platform may help to improve breast cancer detection, hence to discriminate between healthy and disease status." (PMID 25875093, 2015). "IGF-1 induces anterior gradient 2 (AGR2) in the breast cancer MCF7 cell line, through an estrogen response element and a leucine zipper transcription factor-binding site on the AGR2 promoter playing a key role in IGF-1-induced breast cancer cell proliferation and migration." (PMID 26225961, 2015). "There are abundant reports on the modulation of AGR2 expression in breast cancer; however, AGR2 promoter activation by IGF-1 has not been reported." (PMID 25956506, 2015). "AGR3 transcripts have been detected in lung and pancreas and, resembling AGR2, AGR3 has been reported to be co-expressed with estrogen receptor-α-containing breast cancer cell lines, suggesting it to be a marker for hormone-responsive breast cancer." (PMID 23245351, 2012). "Additionally, in the ER-negative breast cancer cell line, MDA-MB-231, AGR2 was induced under serum starvation and hypoxia, suggesting a role for AGR2 in physiologically relevant stress conditions." (PMID 20525379, 2010). "In breast cancer models, overexpression of AGR2 failed to alter tumor formation in vivo or growth rate in vitro, but, rather, reduced cell adhesion and increased the numbers of metastases." (PMID 20525379, 2010). "Indeed, AGR2, LCP1 and S100P overexpression have been previously correlated with breast cancer progression, and we now link the aberrant expression of these genes with ErbB2 expression." (PMID 20840765, 2010). "Although this is the first time a role for AGR2 has been demonstrated in breast cancer cell growth, these results are consistent with the impact of AGR2 knockdown on cell growth reported in other non-breast cancer models." (PMID 20525379, 2010). "Moreover, when tested by Western blotting techniques, the rabbit antiserum reacts with only a single band of 18 kDa in extracts of selected positively staining carcinomas and in the breast cancer cell line MCF-7, in agreement with previous results for AGR2." (PMID 16598187, 2006). "In addition, in a group of 225 ER positive breast cancer patients treated with tamoxifen, the survival rate of patients with AGR2 positive in breast cancer cells was lower than that of patients with AGR2 negative." (PMID 37197416, 2023). "Induction of ER stress in breast cancer cells enhanced the AGR2‐PDIA3 complex formation and increased extracellular levels of AGR2, thus suggesting that the AGR2‐PDIA3 interaction might contribute to AGR2 secretion." (PMID 37409695, 2023).
breast cancer (continued). "Therefore, it remains to be explored whether there is a statistical interaction between AGR2 and FOXA1 on the prognosis of breast cancer." (PMID 37568077, 2023). "It is also interesting to note that both the AGR2 and AGR3 genes are located side-by-side in chromosome 7p21 and are in close proximity to EsR binding sites, therefore it is not surprising that the genes are co-expressed particularly in EsR positive breast cancer." (PMID 35965326, 2022). "Interestingly, circPVT1 is also upregulated in cell lines and tissues of breast cancer; it promotes proliferation, invasion, and migration and inhibits apoptosis through the AGR2–HIF-1α axis mediated by miR-29a-3p; therefore, this circRNA functions as an oncogene in breast cancer." (PMID 36379920, 2022). "In addition, shorter RFS was significantly associated with high expression of both AGR2 and LINC02273, suggesting combined expression levels of AGR2 and LINC02273 may serve as promising biomarkers to determine prognosis in breast cancer." (PMID 31856843, 2019). "The close interplay between the UPR and the TNF pathway, plus recent findings that show that TNF-alpha can prevent in vivo breast cancer development, suggest that downregulation of the TNF pathway in AGR2-overexpressing breast cancers may contribute to their hormone therapy resistance." (PMID 29796176, 2018). "Furthermore, while ESR1 can initially upregulate AGR2 expression, breast cancer cells that achieve tamoxifen resistance no longer require ESR1 for AGR2 expression, likely due to an alteration in the activity of the transcription factor FOXA1." (PMID 29796176, 2018). "However, thus far the potential utility of AGR2 protein as a serum biomarker for breast cancer has not yet been investigated." (PMID 25875093, 2015). "AGR2 warranted further evaluation of its biology based collectively on its prevalence in breast cancer, its negative correlation with patient survival within the ER-positive breast cancer subpopulation, and literature implications of a functional role in cancer." (PMID 20525379, 2010). "Another possibility is that the soft-agar assay measures AGR2-dependent biologies that are not captured in the other assays, a concept consistent with distinct breast cancer models, in which AGR2 overexpression was reported to play a role in metastases and adhesion, but not growth." (PMID 20525379, 2010). "Interestingly, despite its normally restricted expression, elevated AGR3 levels have been observed in estrogen receptor-positive breast cancers, both within cells and in secreted forms, raising the possibility that AGR3 acts as an ER foldase for cell surface receptors, analogous to AGR2." (PMID 40867591, 2025). "So far, AGR2 participates in various tumor processes, such as differentiation, proliferation, migration, invasion and metastasis, and plays an important role in the progress and prognosis of breast cancer through its overexpression and non-canonical localizations." (PMID 37197416, 2023). "miR-194-5p might not be a direct regulator of AGR2 in breast cancers." (PMID 30665445, 2019). "However, human AGR2 has been reported previously to be expressed in the oestrogen receptor alpha (ERα)-positive cell line MCF-7 but not in an ERα-negative cell line, and preliminary studies in human breast cancers also suggest that AGR2 is correlated with expression of ERα." (PMID 16598187, 2006). "We also examined RNA-Seq data of human breast cancer cell lines (provided by Dr. Joe Gray, OHSU) and found no positive correlation in transcript-level expression between AGR2 and dystroglycan (data not shown)." (PMID 33717413, 2021). "In breast cancer cells showing robust expression of AGR2 (i.e. MCF7 and MDA-MB-453), β-DG subunit was clearly up-regulated, whereas it was unchanged in cells expressing little or no AGR2 (i.e. MDA-MB-231)." (PMID 33717413, 2021).
breast cancer (continued). "In the BRCA samples of TCGA, we also noticed a significant relationship between AGR2 expression and FOXA1 gene copy number, as well as several cancer gene copy numbers localized at 14q such as NFKBIA, SAV1, CHD8 or AJUBA, which are not known as driver oncogenes or TSG in breast cancer." (PMID 35857928, 2022). "The differential impact of staining for AGR2 on prognosis in ERα-positive and ERα-negative patients is in contrast to the adverse effect of staining for S100A4 and OPN on the survival of patients with breast cancer which are apparent in both ERα-positive and ERα-negative subgroups." (PMID 16598187, 2006).
prostate carcinoma (46 papers, 2003 to 2024). A carcinoma that arises from epithelial cells of the prostate gland. "In breast and prostate cancer, AGR2 expression has been linked to estrogen receptor and androgen receptor regulation." (PMID 39533806, 2024). "AGR2 is associated with prostate cancer differentiation as Gleason 3 (well-differentiated) cancer cells show a 10-fold higher level than Gleason 4 (less differentiated) cancer cells." (PMID 34911496, 2021). "Aside from the wild-type AGR2 transcripts A and B, other variants, namely, C, E, F, G and H, were also detected in the prostate cancer cell line PC-3." (PMID 31247903, 2019). "In prostate cancer, several miRNAs (such as miR-21 and miR-107) and mRNA (AGR2 splice variant, PCA3, and TMPRSS-ERG) have been reported to be biomarkers in urinary EVs11." (PMID 28211531, 2017). "Like prostate cancer, high AGR2 expression is associated with low grade and low expression with high grade." (PMID 26445321, 2015). "These improvements together have led to the identification of two distinct splice variants of AGR2 in urine exosomes as highly significant in distinguishing between benign and prostate cancer." (PMID 25237833, 2014). "AGR-2 has been found to be over-expressed in various adenocarcinomas and has been linked to poor survival of patients with breast and prostate cancers." (PMID 24587138, 2014). "We then performed comparative AGR2 variant transcript analyses in urine exosomes and urine sediments from 5 prostate carcinoma patients." (PMID 25237833, 2014). "In particular, AGR2 has previously been found to be one of several genes that encode secreted proteins showing increased expression in prostate cancer cells compared to normal prostatic epithelium." (PMID 21144054, 2010). "In prostate cancer cell lines, the expression of the androgen receptor and the metastasis associated protein AGR2 has been demonstrated to be decreased by ectopic expression of Ebp1." (PMID 19094237, 2008). "Similarly, AGR2 has been associated with the propensity of a number of aggressive tumor types to metastasize, including prostate cancer." (PMID 33585078, 2021). "However reports that two splice variants of AGR2 (Δ 6 and Δ 4-6) are selectivity expressed in distinct hepatocellular neoplasms provided hints that analyzing prostate cancer specific splice variants of AGR2 might improve the specificity of this biomarker." (PMID 25237833, 2014). "eAGR2 expression has been identified in pancreatic cancer, gastrointestinal mucinous tumors, and prostate cancer models, where AGR2 is directly expressed within the TME and secreted by cancer cells." (PMID 39062458, 2024). "For example, the range of reported AGR2‐positive cases ranged from 56.8% to 100% in adenocarcinoma of the lung, from 57.0% to 95.4% in prostate cancer, and from 19.0% to 46.1% in serous carcinoma of the ovary." (PMID 39533806, 2024). "Its elevated expression occurs in a number of malignancies compared to healthy tissue and, for instance, AGR2 is a marker of poor prognosis in breast and prostate cancer." (PMID 36142758, 2022). "A decrease in miR-215 levels is correlated with an increase in KDM1B levels in enzalutamide-resistant prostate cancer cells that promotes AR-dependent AGR2 transcription and regulates the sensitivity to AR-targeted therapy." (PMID 36467881, 2022). "Another study reported that the abrogation of AGR2 reduced the attachment of prostate cancer cells to ECM proteins including fibronectin and laminin." (PMID 33717413, 2021). "Another rather exciting finding is the production of two humanized monoclonal anti-AGR2 antibodies, when incubated with human blood, resulting in cell lysis of prostate cancer cells containing eAGR2." (PMID 33005802, 2020). "The EMT-stimulating effect of AGR2 in prostate cancer cells was explained by AGR2-conferred stabilization of protein p65, which, as a result, was able to activate NFκB, thereby promoting EMT." (PMID 32268506, 2020).
prostate carcinoma (continued). "In the case of prostate cancer, secreted AGR2 was shown to stimulate angiogenesis by enhancing VEGF receptor 2 activity and facilitate metastasis spread." (PMID 32268506, 2020). "More importantly, apart from functioning as a part of the RAD9A-HUS1-RAD1 complex, RAD9A independently drives prostate cancer metastasis by controlling AGR2 abundance." (PMID 33575255, 2020). "In prostate cancer, AGR2 expression in a tissue microarray assay was revealed to be increased in 66 prostate cancer adenocarcinoma tissues compared with normal prostatic glandular epithelium tissue." (PMID 31247903, 2019). "The expression of the AGR2 protein in the prostate cancer cell line PC-3 was shown to be controlled by RAD9A through its specific binding to the 5ʹ-untranslated region of AGR2, and the knockdown of RAD9A resulted in the downregulation of AGR2." (PMID 31247903, 2019). "The inhibition of the AGR2 protein in the prostate cancer cell lines PC-3, DU145 and LNCaP upregulated P21 expression." (PMID 31247903, 2019). "The transcriptional factors forkhead box A1 and 2 (FOXA1 and FOXA2) were shown to upregulate the expression of the AGR2 gene in the LNCaP prostate cancer cell line." (PMID 31247903, 2019). "In the prostate cancer cell line PC-3, secreted AGR2 was shown to enhance vascular endothelial growth factor receptor (VEGFR) activity through the formation of disulphide bonds." (PMID 31247903, 2019). "AGR2 is an adenocarcinoma gene upregulated in primary prostate cancer cells, while PENK is a prostate stromal cell-specific gene absent in tumors; both are candidate signaling molecules in prostate stromal/epithelial interaction." (PMID 31146720, 2019). "We dosed PC-3 and LNCaP prostate cancer cell lines with Δ27 AGR2 (100 ng/mL), which is comparable to the levels of eAGR2 in men with castrate resistant metastatic prostate cancer." (PMID 29937991, 2018). "In prostate cancer, a majority of primary prostate tumors show elevated expression of anterior gradient 2 (AGR2)." (PMID 27283903, 2016). "AGR2 is secreted as a 19 kDa protein by prostate cancer cells measurable at pg/ml levels in the urine, and blood of patients." (PMID 26894971, 2016). "CD10 was investigated because of its importance in lymph node spread of prostate cancer cells, and its diametrically opposite role to that of AGR2 in the local vs. distal spread of tumor." (PMID 26894971, 2016). "AGR2 was found to be the most abundant secreted proteins of <20 (besides prostate-specific antigen, prostatic acid phosphatase) produced by prostate cancer cells." (PMID 27283903, 2016). "AGR2 was identified as a biomarker candidate in prostate cancer by comparative transcriptomic analysis of sorted CD26+ cancer cells vs. CD26+ luminal cells." (PMID 26894971, 2016). "AGR2 expression in normal urothelial cells is comparatively lower than that in prostate cancer cells." (PMID 26894971, 2016). "We are currently devising a protocol to purify AGR2 from tissue culture media of prostate cancer cell lines PC3 or CL1 for use in future experiments." (PMID 27283903, 2016). "The positive control of collagenase digestion media of prostate cancer xenograft LuCaP 23.12 tumor contained a level of AGR2 at 25-fold higher than that of the buffer." (PMID 26894971, 2016). "The LuCaP prostate cancer xenograft lines established from primary neoplasm and metastases were either AGR2+ adenocarcinoma or AGR2− small cell carcinoma." (PMID 27283903, 2016). "In the culture experiments, the source of AGR2 was prostate primary tumors, prostate adenocarcinoma xenografts, as well as prostate cancer metastases." (PMID 27283903, 2016). "In bladder cancer, expression of AGR2 is absent in ~75 % cases; normal urothelial cells have moderate AGR2 expression (in comparison to that in prostate cancer cells)." (PMID 26445321, 2015).